SANBR (SANT and BTB domain regulator of CSR)
Description:
Negatively regulates class switch recombination or isotype switching in splenic B-cells.
Synonyms: KIAA1841
Tractability: PROTAC: ubiquitination databases record sites on it.
Gene: Protein-coding gene on chromosome 2 (61,065,871 to 61,138,034, forward strand). Ensembl gene ENSG00000162929.
Subcellular location (Human Protein Atlas): Nucleoli; Nucleoplasm
Gene Ontology:
Molecular function: identical protein binding
Biological process: isotype switching
Genetic constraint (gnomAD): Loss-of-function variants: 24 observed, 34.19 expected, observed/expected ratio (o/e) 0.7, 90% interval 0.51 to 0.99. The upper end of that interval is the gene's LOEUF score, 0.99, which puts it in group 4 of 6, group 1 being the genes least tolerant of losing a copy. Missense variants: 401 observed, 386.59 expected, observed/expected ratio (o/e) 1.04, 90% interval 0.95 to 1.13. Synonymous variants: 108 observed, 125.39 expected, observed/expected ratio (o/e) 0.86, 90% interval 0.74 to 1.01.
Homologues: Orthologues: chimpanzee SANBR (99% identical), macaque SANBR (98% identical), guinea pig SANBR (93% identical), dog SANBR (93% identical), pig SANBR (92% identical), rabbit SANBR (92% identical), mouse Sanbr (89% identical), rat Sanbr (87% identical), tropical clawed frog sanbr (71% identical), zebrafish sanbr (60% identical), Drosophila melanogaster CG6761 (27% identical).
Diseases named in the same sentence as SANBR in open-access papers:
SANBR is named in the same sentence as 3 diseases in open-access papers, as found by Europe PMC text mining. Sharing a sentence is not in itself a finding about the gene and the disease. The quoted sentences say what the papers report.
peroxisome biogenesis disorder (1 paper, 2023). "SANBR (SANT and BTB domain regulator of CSR, also known as KIAA1841) is known for its association with peroxisome biogenesis disorder." (PMID 37055782, 2023).
SANBR also shares sentences with these, for which no sentence is quoted: tumor (2 papers); breast tumor (1).